SATB2 (SATB homeobox 2)
Diseases named in the same sentence as SATB2 in open-access papers (continued):
Sharing a sentence is not in itself a finding about the gene and the disease.
tumor (continued). "Recent studies have demonstrated that SATB2 functions as a tumour promoter by enhancing the expression of c‐Myc, KLF4, Oct4, Sox2 and Nanog." (PMID 32885593, 2020). "Among the 20 SATB2-positive SBAs, the percentage of positive tumor cells ranged from 5% to 70%, with a mean of 27% positive tumor cells (mean H-score of 54)." (PMID 33228145, 2020). "To interrogate the potential relationship between the expression of NMPs and GBM tumor development, we queried the expression pattern of NMPs in clinical database and found that SATB2 (the Special AT‐rich Binding Protein‐2) is enriched in GBMs." (PMID 33124191, 2020). "SATB2 immunostaining showed tumor cell immunoreactivity in 20 SBAs (20%), defined as weak, moderate and strong in ten, eight and two SBAs, respectively." (PMID 33228145, 2020). "To confirm the preferential expression of SATB2 in GSCs, we assessed SATB2 expression in isolated GSCs and matched non‐stem tumor cells (NSTCs) that were functionally validated as described in Materials and Methods." (PMID 33124191, 2020). "Collectively, these data demonstrate that SATB2 disruption potently suppresses the GSC‐driven tumor growth, indicating that SATB2 is critical for maintaining the tumorigenic potential of GSCs in vivo." (PMID 33124191, 2020). "For example, other factors or regulators can act with SATB2 to regulate stemness which provides a link between tumour antigenicity, immune suppression, intratumoural heterogeneity and the resulting trajectories in human cancer." (PMID 32885593, 2020). "Higher expression of SATB2 in neuroendocrine neoplasms is restricted to well‐differentiated tumours of lower gastrointestinal tract origin and is most frequent in Merkel cell carcinoma among poorly differentiated carcinomas." (PMID 32885593, 2020). "We next employed the colony formation assay using HCC cell lines to demonstrate the tumour suppressive effects of SATB2." (PMID 31602781, 2019). "miR-34a, a putative tumor suppressor miRNA that has been shown to repress tumor growth and metastasis, shares identical seed sequences and target genes with miR-449a, such as SATB2, Sirt1 and HDAC1." (PMID 29254139, 2017). "Our recent studies reported a tumor-suppressing function of SATB2 in CRC via the inactivation of MEK5/ERK5 signaling." (PMID 26701851, 2016). "We next examined the expression of SATB2, Oct-4, Nanog, c-Myc and Sox-2 in tumor tissues harvested from HPNE/SATB2 groups by immunohistochemistry." (PMID 27472393, 2016). "Ectopic expression of c-Myc in SATB2 cells (SATB2/Myc) restored the tumor volume and weight compared with that of SATB2 cells." (PMID 26701851, 2016). "The results of the current study showing a tumor-suppressing function of SATB2 in HT29 cells are consistent with our recent reports concerning the function of SATB2." (PMID 26701851, 2016). "Our studies will enhance our understanding of the role of SATB2 in malignant transformation, tumor growth and metastasis." (PMID 27472393, 2016). "Studies of in vivo xenograft tumors also confirmed the tumor-promoting role of c-Myc expression in SATB2-expressing cells." (PMID 26701851, 2016). "SATB2-expression was seen in 3/107 pancreatobiliary type primary tumours, and in 8/61 intestinal type primary tumours." (PMID 25323550, 2014). "In this study, we explored the role of miR-182 in CRC and found that the up-regulation of miR-182 promoted the proliferation, invasion, and metastasis of tumor cell by suppressing SATB2 in CRC." (PMID 24884732, 2014). "SATB2-expression was only seen in 3 out of 107 PB-type tumours, making the statistical analyses hazardous to interpret." (PMID 25323550, 2014). "Cell growth curve assay and colony formation assay were used to verify the effect of SATB2 on the proliferation and tumor progression ability of HEp2 cells." (PMID 22815795, 2012). "The results showed that SATB2 expression, surgical margin and tumor recurrence were recognized as independent prognostic factors of survival." (PMID 22815795, 2012).
tumor (continued). "The reduced expression of SATB2 in MSI tumours is consistent with studies on other markers of colorectal lineage, for example, CDX2 and CK20." (PMID 22333599, 2012). "A strong, signficant association was however seen between SATB1 expression and MSS tumours (p = <0.001), beta-catenin overexpression (p = <0.001) and SATB2 expression (p = <0.001)." (PMID 22935204, 2012). "In vitro experiments demonstrated that over-expression of SATB2 in HEp2 cells inhibited cell proliferation and tumor progression ability, and down-regulation of SATB2 showed the opposite effects." (PMID 22815795, 2012). "This revealed a significantly improved 5-year OS compared with all other strata for patients with SATB2 high tumours receiving adjuvant chemotherapy and/or neoadjuvant therapy." (PMID 22333599, 2012). "Tumor formation assay in nude mice was used to analyze the effect of SATB2 on the tumorigenicity of HEp2 cells." (PMID 22815795, 2012). "The postulated effects of miR-31 on SATB2 and TIAM1 are consistent with the associations between miR-31 expression and advanced tumor stage, observed by us and others, but clearly, the regulatory activity of miR-31 is still incompletely understood in CRC." (PMID 23121918, 2012). "The expression of SATB2 mRNA was also demonstrated to increase with increasing tumour grade, grade 1 vs. grade 3 (normalized mean copy number 0.0380 vs. 0.169, p = 0.035)." (PMID 19642980, 2009). "Through transcriptomic and immunohistochemical analyses, SATB2 was also detected in CRC tissues, although its expression levels were markedly lower than those in normal tissues, which suggested that SATB2 might function as a tumor suppressor in CRC." (PMID 40636538, 2025). "The results indicated that the tumor inhibition rate (both volume and weight) of the Sh-SATB2+IR group (vs. the Sh-SATB2 group) was more obvious than that of the NC+IR group (vs. the NC group), with a volume inhibition rate of 66.88% and a mass inhibition rate of 73.03%." (PMID 40078194, 2025). "To investigate whether SATB2 is hypermethylated in CRC tumor tissues, we used MethSurv, which contains the methylation information of 35 CpG sites for SATB2, to explore the methylation data of CRC in TCGA." (PMID 40636538, 2025). "Additionally, the methylation state of SATB2 was correlated with tumor differentiation and metastasis." (PMID 40636538, 2025). "Although most CRC tumor and adjacent normal tissues were positive for SATB2 expression, the protein expression level of SATB2 in most CRC tumor tissue samples was lower than that in their normal counterparts, which was consistent with the mRNA expression pattern of SATB2." (PMID 40636538, 2025). "The reduced expression of the SATB2 gene in CRC tissues compared to paired normal, uninvolved large intestine tissues, as well as its decreased expression in high-grading tumors, support a tumor suppressor role of SATB2 and involvement of its impaired expression in the pathogenesis of CRC." (PMID 40076993, 2025). "Finally, a mouse subcutaneous xenograft tumor model was employed to elucidate the role of SATB2 on the radiotherapy resistance of ESCC in vivo." (PMID 40078194, 2025). "Conversely, SATB2, known for its reciprocal expression profile, functions as a tumor suppressor." (PMID 40689929, 2025). "Also, the expression profile of SATB2 in tumor tissues compared to normal tissues varies by tumor type." (PMID 40076993, 2025). "Moreover, we also found that apoptosis was significant in tumor tissues in the Sh-SATB2+IR group following SATB2 silencing and radiotherapy." (PMID 40078194, 2025). "To explore whether the promoter region of SATB2 was hypermethylated in CRC tumor tissues, we first predicted the CpG island in the promoter region of SATB2 and designed MSP primers via MethPrimer." (PMID 40636538, 2025). "One case (3.8%) showed very focal expression of SATB2 (1% of tumor cells)." (PMID 41321186, 2025).
tumor (continued). "The unique expression patterns of SATB1 and SATB2 proteins in the tumor samples further support our hypothesis regarding statin-mediated modulation of the canonical Wnt pathway." (PMID 40689929, 2025). "Additional immunostaining with SATB2 showed clear nuclear positivity in some of the tumor cells." (PMID 40522461, 2025). "Our immunohistochemistry results showed that the tumor cells diffusely expressed SATB2 and CD56." (PMID 39866529, 2025). "SATB2 deletion increased ROS-induced apoptosis and reduced tumor proliferation." (PMID 39769005, 2024). "Our GBMO also recapitulated the presence of SATB2+ tumor cells known to drive GBM pathology." (PMID 38384384, 2024). "There was minimal staining of CD80 and SATB2 in the tumour compartment." (PMID 38635728, 2024). "We found that SATB2 was indeed overexpressed in most tumor tissues." (PMID 37107669, 2023). "The positive expression rates of SATB2 in POMCs and MGMCs derived from upper gastrointestinal tract primary tumours were only 3.1% (1/32) and 4.3% (1/23), respectively, and the positive expression rate was up to 90.5% (19/21) in MGMCs from lower gastrointestinal tract tumours (P < 0.001)." (PMID 36639622, 2023). "SATB2 expression in OSCC was associated with metastasis and tumour progression." (PMID 37242569, 2023). "Our main hypothesis states that the expression of CK7, Napsin-A, TTF1, CK20, CDX2, and SATB2 in lung tumours is dependent on the tumour’s site of origin." (PMID 35027072, 2022). "SATB2 has been identified as a tumor suppressor and promoter in cancer." (PMID 36530971, 2022). "Patient 5 had heterogenous SATB2 expression with the highest expression seen in the primary tumour." (PMID 35169225, 2022). "For NSCLC patients, a low expression SATB2 is related to poor prognoses and may promote tumor progression through epithelial-to-mesenchymal transition." (PMID 36530971, 2022). "Finally, we show SATB2 transcriptional rewiring to functionally drive enhanced tumor propagation and resistance to MAPK inhibition by Vemurafenib in zebrafish tumor allografts in vivo." (PMID 33527896, 2021). "SATB2 is a transcription factor that can regulate gene expression by modulating chromatin structure, which plays significant roles in craniofacial morphogenesis, cleft palate formation, and many tumor diseases." (PMID 34483137, 2021). "miRNA‐211, miR‐4270‐5p and miR‐449a inhibited the progression of HCC and CRC by down‐regulating SATB2 expression, and overexpression of SATB2 counteracted the inhibitory effects of these miRNAs on cell proliferation and tumour growth, suggesting the oncogenic potential of SATB2 in cancer." (PMID 32885593, 2020). "Disrupting the SATB2/CBP complex significantly inhibited tumor growth by inhibiting FOXM1 expression, indicating that targeting the SATB2/CBP signaling axis may have therapeutic potential to improve GBM treatment." (PMID 33124191, 2020). "Finally, it was reported the special AT-rich sequence-binding protein 2 (SATB2) as a new tumor-suppressive gene playing an important role in many cancers, including GC." (PMID 32326163, 2020). "Our analysis of clinical database indicated that SATB2 is enriched in GBMs, suggesting that SATB2 may play a tumor‐promoting role in GBMs." (PMID 33124191, 2020). "Moreover, genetic targeting or pharmacological inhibition of SATB2/CBP function significantly suppresses GSC‐driven tumor growth." (PMID 33124191, 2020). "However, SATB2 promotes tumor growth in hepatocellular carcinoma, osteosarcoma, and triple‐negative breast cancer." (PMID 33124191, 2020). "Our study indicates that the SATB2/CBP transcriptional complex plays critical roles in maintaining GSC property to sustain GBM tumor growth, suggesting that targeting the STAB2/CBP signaling axis may significantly improve survival of GBM patients." (PMID 33124191, 2020).
tumor (continued). "In this study, liver markers (AFP, Hepatocyte, Glypican-3, and GS) and colon markers (CK20, CAD17, CDX2, β-catenin, and SATB2) were used for staining of xenograft-derived tumours, with the result that all markers were either expressed only weakly, or were not express at all." (PMID 31367188, 2019). "To determine whether miR-449a mediates its growth-suppressive effects primarily by downregulating SATB2, we overexpressed SATB2 in tumor cells overexpressing miR-449a." (PMID 29254139, 2017). "SATB2 inhibited tumor growth indirectly via DNMT3A and miR-449a/34a expression." (PMID 29254139, 2017). "Indeed, the tumor cell growth-repressing effects of miR-449a are in part facilitated via the downregulation of SATB2, indicating the existence of other targets that impact tumor growth and that are regulated by miR-449a." (PMID 29254139, 2017). "However, we found that SATB2 knockdown significantly suppressed tumor proliferation in xenograft mouse model, suggesting that SATB2 upregulation constitutes an early step in colorectal tumorigenesis and that it plays different roles in tumor progression." (PMID 29254139, 2017). "Yang and colleagues confirmed that overexpression of miRNA-182 enhanced the proliferative and metastatic capabilities of CRC cells by targeting the 3′-UTR of special AT-rich sequence binding protein 2 (SATB2) and caused tumor cells to undergo epithelial-mesenchymal transition (EMT)." (PMID 28115926, 2016). "In I-type tumours, SATB2-positivity was seen in 8 out of 61 cases." (PMID 25323550, 2014). "SATB2 expression was significantly correlated with histological grade and tumor recurrence." (PMID 22815795, 2012). "The expression level of SATB2 mRNA is significantly lower in tumor tissues." (PMID 22815795, 2012). "The association between SATB1 expression and adverse outcome in SATB2 negative tumours is of potential significance, although based on a post-hoc analysis in a rather small subgroup." (PMID 22935204, 2012). "Besides SATB2 expression level, age, thyroid cartilage invasion, T stage, pathological stage, histological grade, surgical margin, radiotherapy, and tumor recurrence were also significantly correlated with overall survival in univariate analysis." (PMID 22815795, 2012). "Similar to SATB2, SATB1 expression was associated with microsatellite stable tumours." (PMID 22935204, 2012). "However, the expression of SATB1, a close homologue of SATB2, is significantly upregulated in most of these tumor samples." (PMID 22815795, 2012). "The vast majority of tumours with strong SATB2 intensity had a nuclear fraction of >75% and only a few had a nuclear fraction of 50–75%, hence the low number (n=4) of tumours denoted as having NS=9, whereas an NS of 8 (n=104) would correspond to moderate staining in >75% of tumour cells." (PMID 22333599, 2012). "Our study suggests that lower SATB2 expression might be positively correlated with worse tumor biological features, such as rapid tumor progression and metastases, and that SATB2 plays an important role in the development and progression of LSCC." (PMID 22815795, 2012). "Additionally, we have shown that SATB2 expression was positively correlated with histological grade, and tumor recurrence, and that SATB2 expression was also a trend toward potential correlation with lymphatic metastasis (P = .098)." (PMID 22815795, 2012). "Following antibody optimisation and staining, SATB2 expression could be evaluated in 527 out of 557 (94.6%) of the tumours represented in the TMA." (PMID 22333599, 2012). "Combined the results form our study and Wang’s study, SATB2 might be related to tumor differentiation." (PMID 22815795, 2012). "Notably, SATB2 was also abundantly expressed in all these tumours, with a NS = 12 in 15/18 cases and a NS = 8 in 3 cases." (PMID 22935204, 2012). "SATB2 expression increased with increasing tumour grade (grade 1 vs. grade 3 p = 0.035)." (PMID 19642980, 2009).
tumor (continued). "Previous reports on the involvement of SATB2 in various cancers indicated a cancer-specific role and expression of SATB2, identifying either its tumor-promoting function and increased expression in some cancer types or its tumor-suppressor role and decreased expression in others." (PMID 40076993, 2025). "Interestingly, a significant fraction of tumor cells expressed the transcription factor SATB2." (PMID 40205657, 2025). "In addition to reduced SATB2 protein immunoreactivity, we also observed decreased SATB2 transcript content in tumor tissues, which is in line with the findings of other authors and advocates a tumor suppressor role for SATB2." (PMID 40076993, 2025). "Interestingly, SATB2 low/absent CRCs were associated with an especially aggressive disease course in CRCs with high tumour budding activity and in UICC stage III cancers and showed highly reduced survival times in these high-risk subgroups." (PMID 34944797, 2021). "As pharmacological inhibition of SATB2/CBP function markedly inhibited GBM tumor growth, therapeutic targeting of the SATB2/CBP‐FOXM1 signaling axis may offer an effective strategy to significantly improve therapeutic efficacy for GBMs and prolong survival of the patients." (PMID 33124191, 2020). "In addition, we do not find any association between SATB2 expression and AJCC tumor stage or between SATB2 and tumor site, although previous studies reported a higher percentage of SATB2-positivity among jejunal/ileal cases compared to duodenal SBAs." (PMID 33228145, 2020). "Importantly, inhibition of SATB2/CBP transcriptional activity by the CBP inhibitor C646 significantly suppressed GSC proliferation and GBM tumor growth, indicating that targeting SATB2/CBP may be an effective therapeutic strategy to improve GBM treatment." (PMID 33124191, 2020). "Thus, inhibiting the transcriptional activity of SATB2/CBP by the CBP inhibitor potently suppresses GBM tumor growth, suggesting that targeting this signaling axis may be a promising therapeutic strategy to effectively improve GBM treatment." (PMID 33124191, 2020). "Additionally, the incidence of SATB2 protein expression in well-differentiated carcinoma was significantly higher than that in poor-differentiated tumors, and SATB2 expression was significantly related with tumor differentiation (P = .002)." (PMID 22815795, 2012). "Nevertheless, the putative treatment predictive role of SATB2 should preferably be validated in tumour specimens from randomised, controlled treatment trials and the molecular basis for how SATB2 might modulate the effects of chemotherapy and radiation also remains to be elucidated." (PMID 22333599, 2012). "Immunohistochemistry (IHC) staining of patient tumor sections and immunofluorescence (IF) staining of organoid sections for CD99, VIM, CD68, KI67, and SATB2 showed positive expression in both, confirming histopathological similarities." (PMID 40476445, 2025). "These tumours frequently retained positive staining for MUC-1, MUC-2, SATB2 and TFF-3, suggesting that these tumours maintain some degree of intestinal differentiation." (PMID 40935920, 2025). "Next, we explored the methylation status of the SATB2 promoter and SATB2 expression patterns in the collected CRC tumor and adjacent normal tissues, as well as different cell lines, via methylation‐specific PCR and quantitative PCR." (PMID 40636538, 2025). "Immunohistochemistry (IHC) for further characterization showed the tumor was positive for CDX2, CK20, and SATB2." (PMID 41328080, 2025). "The tumour cells showed positive staining for calretinin (Ventana; clone SP65, RTU), with very focal positive staining for SATB2 (Master Diagnostica; clone EP281, RTU)." (PMID 40935920, 2025). "Although the effect of statins on SATB2 expression was less pronounced compared to SATB1, the dynamic expression patterns of both proteins were disrupted in tumor tissues and 3D spheroids." (PMID 40689929, 2025).